H3Y1 (H3.Y histone 1)
Description:
Primate-specific variant histone H3, which constitutes a core component of nucleosomes. Histone H3.Y-containing nucleosomes accumulate around transcription start sites and have flexible DNA ends, suggesting that they form relaxed chromatin that allows transcription factor access. Histone H1 binds less efficiently to histone H3.Y-containing nucleosomes. Nucleosomes wrap and compact DNA into chromatin, limiting DNA accessibility to the cellular machineries which require DNA as a template. Histones thereby play a central role in transcription regulation, DNA repair, DNA replication and chromosomal stability. DNA accessibility is regulated via a complex set of post-translational modifications of histones, also called histone code, and nucleosome remodeling (Probable).
Synonyms: H3.Y; H3.Y.1
Tractability: No criterion of Open Targets' tractability assessment is met for any kind of drug.
Gene: Protein-coding gene on chromosome 5 (17,654,868 to 17,655,849, reverse strand). Ensembl gene ENSG00000269466.
Subcellular location: Nucleus; Chromosome
Subcellular location (Human Protein Atlas): Nucleoplasm
Gene Ontology:
Molecular function: nucleosomal DNA binding; structural constituent of chromatin; DNA binding; protein heterodimerization activity
Biological process: heterochromatin formation; kinetochore assembly; mitotic metaphase chromosome alignment
Cellular component: chromosome; nucleoplasm; nucleosome; nucleus; kinetochore
Homologues: Orthologues: Drosophila melanogaster His3.3A (81% identical), Drosophila melanogaster His3.3B (81% identical), guinea pig H3-5 (81% identical), mouse H3f3b (81% identical), pig H3-3A (81% identical), rat H3f3b (81% identical), zebrafish h3f3a (81% identical), zebrafish si:ch1073-429i10.3 (81% identical), Caenorhabditis elegans his-74 (79% identical), Caenorhabditis elegans his-70 (71% identical), Caenorhabditis elegans his-69 (69% identical), rat H3f3bl1 (39% identical). Paralogues in human: H3Y2 (97% identical), H3-3A (81% identical), H3-3B (81% identical), H3C13 (78% identical), H3C14 (78% identical), H3C15 (78% identical), H3-5 (77% identical), H3C1 (77% identical), H3C10 (77% identical), H3C11 (77% identical), H3C12 (77% identical), H3C2 (77% identical), and 8 more.
Diseases named in the same sentence as H3Y1 in open-access papers:
H3Y1 is named in the same sentence as 1 disease in open-access papers, as found by Europe PMC text mining. Sharing a sentence is not in itself a finding about the gene and the disease. The quoted sentences say what the papers report.
HCMV infection (1 paper, 2022). "Transcripts specifically induced by HCMV infection of TOs included H3Y1 (H3.Y Histone 1), KHDC1L (KH Domain Containing 1 Like), several members of the PRAME Family (PRAMEF2, 8, 12, 14, and 20), and TRIM49A and B (Tripartite Motif Containing 43)." (PMID 35975985, 2022).